RNU6-197P (RNA, U6 small nuclear 197, pseudogene)
Gene: Small nuclear RNA gene on chromosome 4 (56,288,485 to 56,288,584, reverse strand). Ensembl gene ENSG00000252489.
Homologues: Orthologues: chimpanzee U6 (100% identical), macaque U6 (95% identical), mouse Gm54684 (62% identical), rat LOC120093303 (59% identical). Paralogues in human: RNU6-1331P (79% identical), RNU6-43P (77% identical), RNU6-727P (77% identical), RNU6-1094P (76% identical), RNU6-1216P (76% identical), RNU6-125P (76% identical), RNU6-1273P (76% identical), RNU6-189P (76% identical), RNU6-31P (76% identical), RNU6-379P (76% identical), RNU6-41P (76% identical), RNU6-944P (76% identical), and 1285 more.